MIR4688 (microRNA 4688)
Synonyms: hsa-mir-4688; mir-4688
Gene: MicroRNA gene on chromosome 11 (46,376,402 to 46,376,484, forward strand). Ensembl gene ENSG00000264102.
Homologues: Orthologues: chimpanzee MIR4688 (100% identical).